EWSR1 (EWS RNA binding protein 1)
Diseases named in the same sentence as EWSR1 in open-access papers (continued):
Sharing a sentence is not in itself a finding about the gene and the disease.
mesenchymal neoplasms (continued). "Rare mesenchymal tumors carrying EWSR1-NFATC2 fusions have been assigned to ESLTs, probably due to partial CD99 expression and/or involvement of the EWSR1." (PMID 31049020, 2019). "Recently, a small series of intracranial mesenchymal tumors with EWSR1-CREB family gene fusions has been reported." (PMID 31139520, 2019). "The NFATC2 gene is one of the many translocation partners of EWSR1 in gene fusions in a morphologically typical, albeit rare, subgroup of mesenchymal tumors." (PMID 31049020, 2019). "On the other hand, EWSR1-CREM fusion was found in a unique myxoid mesenchymal tumor that was recently described as a new entity." (PMID 30219084, 2018). "Although, EWSR1 translocations can be found in many other mesenchymal tumors, almost all of the remaining ES cases are characterized by further ES-specific EWSR1 translocations." (PMID 24879454, 2014). "Promiscuity of EWSR1::ATF1 fusions as well as the polyphenotypic phenotype of this tumor type may lead to diagnostic confusion with both mesenchymal and non-mesenchymal neoplasms." (PMID 39031200, 2024). "In summary, we described four extra-abdominal round cell/epithelioid mesenchymal neoplasms sharing EWSR1::ATF1 fusions, frequent expression of epithelial and neuroendocrine markers, occasional aberrant expression of ALK and MUC4, but not fitting with any currently defined mesenchymal neoplasm." (PMID 39031200, 2024). "Likewise, EWSR1-rearranged myxoid mesenchymal neoplasms of the CNS have distinct histologic features and have a reported propensity for the supratentorial region of adolescents and young adults." (PMID 33738448, 2021). "Fusions between the FET gene family (EWSR1 and FUS) and one of the CREB transcription factor family members (ATF, CREB1, and CREM) have been increasingly reported in a variety of mesenchymal neoplasms that are clinically, anatomically, and phenotypically distinct." (PMID 40748380, 2025). "We identified three tumors in our epigenetically distinct METs group that carried fusions described in molecularly defined, non-MET tumor types, i.e., EWSR1::NFATC2-rearranged mesenchymal neoplasms and IRF2BP2::CDX1-rearranged neoplasm." (PMID 39636306, 2025). "EWSR1/FUS-CREM fusions were recognized recently in a group of unclassified epithelioid mesenchymal neoplasms showing predilection for intra-abdominal organs, not fitting any known EWSR1-CREB-rearranged entity." (PMID 34228212, 2022). "There are still very few reports of gastric epithelioid mesenchymal tumors with EWSR1/FUS::CREB fusion that do not fit the criteria for GNETs, and the collection of additional cases is needed to better understand their epidemiology, symptoms, prognosis, and treatment." (PMID 40242428, 2025). "Consequently, much like in astroblastomas, the EWSR1::BEND2 and MN1::BEND2 fusions may define a distinct subgroup of mesenchymal tumors." (PMID 38339014, 2024).
soft tissue tumors (30 papers, 2010 to 2025). "With the increasing use of next generation sequencing in soft tissue pathology, particularly in neoplasms not fitting any World Health Organization (WHO) category, the spectrum of EWSR1 fusion-associated soft tissue neoplasms has been expanding significantly." (PMID 39031200, 2024). "The EWSR1 gene is one of the genes most sensitive to translocation in soft tissue tumors and encodes the EWS protein, which is a member of a growing family of highly conserved RNA-binding proteins mediating interaction with RNA or single-stranded DNA." (PMID 35926382, 2022). "Each of these soft tissue tumors with EWSR1 rearrangements is associated with characteristic clinical presentations and histopathologic findings." (PMID 26413364, 2015). "One of the genes most susceptible to breakage/translocation in soft tissue tumors is represented by Ewing sarcoma breakpoint region 1 (EWSR1)." (PMID 23329308, 2013). "Chromosome rearrangements involving the EWSR1 locus are believed to be the most frequent ones in clinicopathologically diverse soft-tissue tumors, including certain carcinomas and mesotheliomas." (PMID 39769457, 2024). "As a result, in-frame EWSR1::ATF1 produces the oncogenic EWSR1::ATF1 chimeric protein, which is the cytogenetic hallmark of certain soft-tissue tumors and is often found as the only chromosomal abnormality in the affected neoplasms." (PMID 39769457, 2024). "In general, EWSR1 fusions with various partners are frequent in soft tissue tumors and include rare instances of alternative EWSR1::SSX1 fusion in synovial sarcoma, or potential FUS fusion with POU2AF3 instead of EWSR1." (PMID 38491228, 2024). "We herein describe a unique cohort of soft tissue neoplasms characterized by epithelioid/round cell morphology, unusual immunophenotype, and recurrent EWSR1::ATF1 fusions, all occurring in extra-abdominal deep soft tissue or bone sites." (PMID 39031200, 2024). "When considering that SS had overlapping morphology and immunohistochemistry with EWSR-1 translocation-related soft tissue tumor, SS18 and EWSR-1 gene arrangements were detected for differential diagnosis." (PMID 37193761, 2023). "Our study exemplifies the widespread nature of EWSR1 rearrangements in soft tissue tumours and the need to correlate positive molecular findings with morphology and immunohistochemistry." (PMID 28141799, 2017). "We herein describe a unique cohort of soft tissue neoplasms characterized by epithelioid/round cell morphology, unusual immunophenotype, and recurrent EWSR1/FUS::CREM fusions, occurring in extra-abdominal deep soft tissue (n = 2), head and neck (n = 3), and intraabdominal (n = 4) sites." (PMID 39249507, 2024). "In previous studies, fusion genes such as, EWS-FLI-1, EWSR1-WT1, EWSR1-KLF17, EWSR1-ATF1, and EWSR1-CREB3L1, are known to be produced by rearrangement of the EWSR1 gene with different gene fusion partners and these fusion genes have functions related to a variety of soft tissue tumors." (PMID 27534535, 2016). "Fusion partners of EWSR1-rearrangements in different soft tissue tumors." (PMID 24879454, 2014). "Regarding EWSR1 breakpoints, not all the regions composing the protein are susceptible to breakage in soft tissue tumors." (PMID 23329308, 2013). "The third GF, EWSR1::BEND2, has previously been reported in a subtype of astroblastoma and other rare entities, including a single case of a soft-tissue tumor that we discuss in this work." (PMID 38339014, 2024). "EWSR1/FUS::NFATC2 rearrangements are promiscuous gene fusions found in both benign and malignant bone and soft tissue tumors." (PMID 36555836, 2022). "As EWSR1 fusions with various partners are frequent in soft tissue tumors, FISH analysis of an EWSR1 break is not a sufficient diagnostic test." (PMID 38217715, 2024).
soft tissue tumors (continued). "The molecular basis of ALK immunoreactivity observed in diverse fusion-associated soft tissue tumors seems heterogeneous and associates with specific types of fusions (e.g., EWSR1/FUS-TFCP2 and EWSR1 but not MEIS1-NCOA2 and other fusions)." (PMID 34228212, 2022). "Several breakpoints have been described for EWSR1 and FLI1 in soft tissue tumors." (PMID 23329308, 2013). "Several breakpoints have been described for EWSR1 and ERG in soft tissue tumors." (PMID 23329308, 2013).
myoepithelial tumor (27 papers, 2011 to 2025). A benign or malignant tumor characterized by the presence of cells that show myoepithelial differentiation. "Chondroid syringomas are considered a cutaneous part of myoepithelial neoplasms that show a variety of genetic alterations, such as gene fusion of EWSR1 with PBX1 in soft tissue originated tumors." (PMID 35225876, 2022). "To confirm that this gene expression signature was present and relevant also in SRF fusion-positive tumors, we analyzed the gene expression profile of two myoepitheliomas carrying SRF::E2F1 chimeric fusion with respect to two EWSR1-rearranged MN." (PMID 36421692, 2022). "Several mutations have been identified, including PLAG1 (pleiomorphic adenoma gene 1 protein) or EWSR1 (Ewing sarcoma breakpoint region 1) gene rearrangements, also found in myoepitheliomas, similar to pleomorphic adenomas." (PMID 34064849, 2021). "RNA sequencing analysis of one previous case showed that the SS18-POU5F1 tumors cluster with EWSR1/FUS-POU5F1-positive myoepithelial tumors, suggesting molecular kinship with this group of tumors." (PMID 34249705, 2021). "EWSR1 rearrangements, also described in mixed tumors, occur in myoepitheliomas in a subset of cases." (PMID 34064849, 2021). "PPMS should be also be distinguished from myoepithelial tumors, which can also arise in the lung with endobronchial growth pattern and EWSR1 rearrangements." (PMID 32039736, 2020). "Approximately 50% of myoepithelial neoplasms harbor EWSR1 fusions with a variety of partner genes (PBX1, PBX3, ZNF44, POU5F1, and ATF1)." (PMID 33114111, 2020). "As would be typical, no fusion transcript involving EWSR1-ATF1 or EWSR1-CREB1 was found in EWSR1 FISH-positive myoepithelial neoplasms." (PMID 28141799, 2017). "According to the literature, nearly half of myoepithelial neoplasm carries EWSR1 translocations to an ever increasing variety of partners." (PMID 28947952, 2017). "EWSR1/POU5F1 translocation is described in myoepithelial tumor of bone, soft tissue, epithelium and myoepithelium." (PMID 23329308, 2013). "Antonescu and co-workers recently showed that gene fusions involving the EWSR1 gene are common in myoepithelial tumors of soft tissue and bone." (PMID 22588017, 2011). "Different from most other EWSR1-rearranged neoplasms, myoepithelial tumors have a normal counterpart, with myoepithelial cells being the outer layer of glands present in e.g., salivary glands, lung, skin adnexa, and mamma, but naturally not in soft tissue and bone." (PMID 34203801, 2021). "EWSR1-PBX3 fusion gene is present in most cases of cutaneous syncytial myoepitheliomas, but EWSR1 rearrangement with unknown fusion partner genes is present in a subset of cutaneous myoepitheliomas." (PMID 32316685, 2020). "Furthermore, although EWSR1::ATF1 is associated with multiple tumors, including angiomatoid fibrous histiocytoma, myoepithelial tumors, hyalinizing clear cell carcinoma, and CCS-like tumors of the gastrointestinal tract, SOX10 expression is relatively specific to CCS." (PMID 37405123, 2023). "An EWSR1 rearrangement was less prevalent in EMC, AFH, PPMS, myoepithelial neoplasms, LGFMS and SEF." (PMID 28141799, 2017). "FISH was most likely to fail in myoepithelial neoplasms (7.1%) and AFH (5.0%) compared to other EWSR1-rearranged neoplasms." (PMID 28141799, 2017). "FISH studies, performed to rule out the possibility of gastrointestinal clear cell sarcoma and a myoepithelial tumor, showed no rearrangement of the EWSR1, FUS, ATF1, and CREB1 genes." (PMID 35001360, 2022). "FUS has been shown to be alternatively present as the N-terminal genetic partner in oncogenic fusions in a small subset of myoepithelial tumors lacking EWSR1 rearrangements." (PMID 33114111, 2020). "Myoepithelial neoplasms (MN) are rare and not well-circumstanced entities displaying a heterogeneous spectrum of genetic abnormalities, including EWSR1, FUS and PLAG1 rearrangements." (PMID 28947952, 2017).
myoepithelial tumor (continued). "EWSR1 and PLAG rearrangements are characteristic genetic changes in myoepithelial tumors." (PMID 24986479, 2014). "Our case adds to the expanding pool of EWSR1-negative myoepithelial tumors of soft tissue." (PMID 40978976, 2025). "EWSR1-negative gene fusions are rarely reported in myoepithelial tumors of soft tissue." (PMID 40978976, 2025). "However, about 45% of myoepitheliomas and myoepithelial carcinomas possess an alteration in the EWSR1 gene unlike PLAG 1 gene alteration noted in chondroid syringoma." (PMID 39618562, 2024). "In three cases of myoepithelioma, FISH for EWSR1 gene rearrangement was performed, but was negative in all, and the diagnosis was made on morphology alone." (PMID 33061792, 2020). "No rearrangement of the EWSR1 and FUS loci was detected as reported in myoepitheliomas." (PMID 29992069, 2018).
leukemia (26 papers, 2008 to 2025). A malignant (clonal) hematologic disorder, involving hematopoietic stem cells and characterized by the presence of primitive or atypical myeloid or lymphoid cells in the bone marrow and the blood. "Together, these orthogonal findings support the prioritization of EWSR1 as the key functional mediator of HHT activity in leukemia cells." (PMID 41472850, 2025). "BLI revealed that tumor burden increased rapidly in the shNC group, while both HHT treatment and EWSR1 knockdown significantly suppressed leukemia progression." (PMID 41472850, 2025). "Although most common in EWS, EWSR1::FLI1 fusions have rarely been described in hematopoietic malignancies including acute leukemias, myeloid sarcoma, and in secondary leukemia after a diagnosis of EWS." (PMID 40630716, 2025). "Taken together, our findings suggest that HHT enhances the interaction between EWSR1 and YTHDF2, thus inhibiting the recognition of the m6A‐modified target genes TNFRSF1B and HMOX1, ultimately leading to apoptosis in leukemia cells." (PMID 41472850, 2025).
myxoid liposarcoma (25 papers, 2012 to 2025). A liposarcoma characterized by the presence of round non-lipogenic primitive mesenchymal cells and small signet ring lipoblasts within a myxoid stoma with a branching vascular pattern. "In vitro studies in EWS and myxoid liposarcoma, another fusion gene holding tumor demonstrated a high efficacy and showed interference with the activity of EWSR1-ETS and EWSR1-CHOP fusion protein, respectively." (PMID 26193259, 2015). "However, targeted RNA NGS unveiled an EWSR1::DDIT3 gene fusion, which is pathognomonic and diagnostic for myxoid liposarcoma." (PMID 38137051, 2023). "Myxoid liposarcoma (MLS) accounts for 20%-30% of all liposarcomas, with most cases harboring the fusion gene FUS::DDIT3, while approximately 5% exhibit the EWSR1::DDIT3 fusion." (PMID 41108625, 2025). "Taking together the histology and immunohistochemistry results and the presence of a specific EWSR1::DDIT3 gene fusion, this case should be considered as a myxoid liposarcoma, at least of intermediate grade because of the increased cellularity in this biopsy." (PMID 38137051, 2023). "For instance, myxoid liposarcoma is characterized by DDIT3 translocation, most commonly fused with FUS gene, while extraskeletal myxoid chondrosarcoma features a recurrent NR4A3 translocation, most frequently translocated to EWSR1 gene." (PMID 35484289, 2022). "Reporter assays showed that the EWSR1-DDIT3 myxoid liposarcoma fusion protein, but not its wild-type counterparts EWSR1 and DDIT3, selectively repressed the transcriptional activity of cell lineage-specific marker genes in multipotent mesenchymal C3H10T1/2 cells." (PMID 22570737, 2012). "Among the EWSR1-negative samples, 29 samples were positive for a FUS rearrangement either by FISH or RT–PCR: 18 cases were diagnosed as myxoid liposarcoma, 9 cases as LGFMS and 2 cases as SEF." (PMID 28141799, 2017).
synovial sarcoma (25 papers, 2005 to 2026). "Alterations involving the EWSR1 gene have also been reported in a small subset of synovial sarcomas." (PMID 40927430, 2025). "While BAF complexes are critical in SS18-SSX-driven synovial sarcomas, we show that EWSR1 and MN1 activate gene expression via a mechanism that can be independent of BAF presence." (PMID 37735617, 2023). "In this study, histology‐specific fusion genes were identified in nine cases, including SYT::SSX1 in synovial sarcoma, EWSR1::FLI1 in ES, and EWSR1::NR4A3 in EMC." (PMID 40755265, 2025).
angiomatoid fibrous histiocytoma (24 papers, 2011 to 2025). "Specifically, MAP3K8 and ALK presented PAX8+ papillary proliferations, ESWR1/FUS::ATF1 and EWSR1::YY1 displayed angiomatoid fibrous histiocytoma-like patterns, while SUFU showcased ‘tissue culture’-like spindle cell proliferation." (PMID 39059063, 2024). "This includes a case of angiomatoid fibrous histiocytoma with EWSR1-CREM fusion, an angiocentric glioma with MYB-QKI fusion, a glioma with MYCN amplification, two patients with non-canonical IDH mutations (both with IDH1 R132S), and a patient with a KRAS mutation." (PMID 38764578, 2024). "For example, in our study, a tumor with a rearranged EWSR1 detected by FISH was initially diagnosed as Ewing’s sarcoma until genomic analysis revealed a EWSR1-CREB1 rearrangement, and the diagnosis was consequently changed to angiomatoid fibrous histiocytoma." (PMID 34771600, 2021). "The final diagnosis must rely on molecular testing, such as FISH detection (EWSR1 break probe) or next-generation sequencing, to determine whether there is EWSR1::CREB family fusion and to pay attention to the final distinction from a morphologically similar angiomatoid fibrous histiocytoma." (PMID 41341384, 2025).
liposarcoma (23 papers, 2012 to 2026). A usually painless malignant tumor that arises from adipose tissue. "In addition to EWSR1-FLI1 expression in Ewing sarcoma, the EWSR1 gene fuses to various genes in other cancers (e.g., EWSR1/ELF5 in acute myeloid leukemia, EWSR1/NR4A3 in extraskeletal myxoid chondrosarcomas, and EWSR1/CHOP in liposarcoma etc)." (PMID 36875767, 2023).
amyotrophic lateral sclerosis (19 papers, 2012 to 2022). "Several studies have shown that EWSR1 is associated with central nervous system disorders, such as amyotrophic lateral sclerosis and frontotemporal dementia." (PMID 36585419, 2022). "Cabeza (caz) is the single Drosophila melanogaster orthologue of the human FET proteins FUS, TAF15, and EWSR1, which have been implicated in amyotrophic lateral sclerosis (ALS) and frontotemporal dementia." (PMID 30209068, 2018). "Such prion-like proteins have been linked to pathomechanisms of amyotrophic lateral sclerosis (ALS) in humans, in particular TDP43, FUS, TAF15, EWSR1 and hnRNPA2." (PMID 36415860, 2022). "In this context, it would be intriguing to note that a number of paraspeckle-enriched RBPs with IDRs, including SFPQ, FUS, EWSR1, TAF15, TDP-43, SS18L1 and HNRNPA1, are mutated in familial cases of amyotrophic lateral sclerosis (ALS) and other neurodegenerative diseases." (PMID 30355755, 2018). "Genetic analyses of patients with amyotrophic lateral sclerosis (ALS) have revealed a strong association between mutations in genes encoding many RNA-binding proteins (RBPs), including TARDBP, FUS, hnRNPA1, hnRNPA2B1, MATR3, ATXN2, TAF15, TIA-1, and EWSR1, and disease onset/progression." (PMID 32547363, 2020). "Mutations in the RBPs, TAR DNA (TARDBP), FUS RNA-binding protein (FUS), Ataxin 2 (ATXN2) as well as EWS RNA-binding proteins (EWSR1) and many more have been shown to greatly influence disease risks, e.g., amyotrophic lateral sclerosis (ALS) and frontotemporal dementia (FDT)." (PMID 35202165, 2022). "FET (FUS-Fused in Sarcoma; EWSR1-Ewings Sarcoma breakpoint region 1; TATA box binding protein Associated Factor 15) proteins have been implicated in neurodegenerative disorders such as Amyotrophic Lateral Sclerosis (ALS) and Fronto-Temporal Lobar Degeneration (FTLD)." (PMID 35440550, 2022).
primitive neuroectodermal tumor (17 papers, 2012 to 2025). A malignant neoplasm that originates in the neuroectoderm. "Recently, ESFT including ES, extraskeletal ES, primitive neuroectodermal tumor, and Askin tumor has been recognized as originating from the primitive neural tube, with a common translocation of the EWSR1 gene at chromosome 22q12." (PMID 36959631, 2023). "Molecular studies, specifically fluorescence in situ hybridization (FISH), are essential to confirm the presence of EWSR1::CREB1, which are characteristic of MGNET and further distinguish it from other neuroectodermal tumors." (PMID 40429661, 2025). "Histopathological analysis revealed a renal small round blue cell tumor (consistent with a primitive neuroectodermal tumor), with positive immunohistochemistry for CD99 and Ki67 (about 10%) and molecular pathology for EWSR1 gene fusions." (PMID 35821028, 2022).